IFNG (interferon gamma)
Diseases named in the same sentence as IFNG in open-access papers (continued):
Sharing a sentence is not in itself a finding about the gene and the disease.
tumor (continued). "The reduced expression of anti-tumour cytokines in CXCL9-treated mice was further proven by the observation that serum level of TNFα, IL2, and IFNγ in CXCL9-treated mice was remarkably suppressed." (PMID 31913856, 2020). "ID-8 induced the death of tumor cells more efficiently than Ipilimumab, by significantly increasing the secretion of IL-2 and IFNγ cytokines by NK cells, and leading to increased cell lysis with a higher lactate dehydrogenase (LDH) release by tumor cells." (PMID 32781690, 2020). "As expected, after A20.GL tumor challenge and CAR T cell treatment, CARneg CD8+ T cells in m1928z-CD40L CAR T cell-treated mice produced more IFNγ after ex vivo phorbol 12-myristate 13-acetate (PMA)/ionomycin stimulation." (PMID 33268774, 2020). "Meanwhile, tumour-infiltrating lymphocytes (TILs: CD8+ T and NK cells) from Gsdme−/− tumours also expressed less granzyme B (GzmB), perforin (PFN), interferon-γ (IFNγ), and TFN." (PMID 32404864, 2020). "In response to several stimuli such as IL-5, IL-33, CCL11, IFNγ and TNFα, eosinophils secrete cytotoxic proteins (MBP, ECP, EDN and granzymes), which can induce apoptosis of tumor cells." (PMID 33233582, 2020). "Under hypoxic conditions, CD8 T cells can differentiate into lytic effector cells, increase the expression of interferon gamma (IFNγ), Fas ligand (FASL), granule B (GZMB), and inhibit tumor cell proliferation 24,25." (PMID 32218698, 2020). "CD8+ cytotoxic T cells (CTLs) and natural killer (NK) cells are primarily responsible for killing tumor cells, while CD4+ helper T cells can enhance their cytotoxic function by producing cytokines such as IFNγ." (PMID 33134306, 2020). "In contrast to the splenocytes, when tumor infiltrated lymphocytes (TIL) are stimulated with p15E, much higher percentage of IFNγ and CD107a expressing cells were observed." (PMID 33584714, 2020). "NO is reported to regulate the expression of various cytokines, growth factors and chemokines, including IL-6, IL-10, IFNγ, TGFβ, M-CSF, VEGF and MCP-1, which are important in tumor growth and metastasis." (PMID 32509271, 2020). "The effect was mediated by the induction of IFNγ-producing CD8+ T cells in the gut and increased infiltration of the tumor by these cells." (PMID 32517213, 2020). "Expression of anti-tumour cytokines, including TNFα, IL2, and IFNγ in sorted CD8+ cytotoxic cells, were measured by quantitative real-time PCR." (PMID 31913856, 2020). "Interferon-gamma (IFN-γ) is produced by CD8+ T-cells upon activation, as well as other inflammatory cells, and is a major effector of anti-tumor activity by enhancing the antigen-presentation machinery and having strong immune stimulatory properties." (PMID 35582440, 2020). "MHC expression is controlled by interferon gamma (IFNγ), which is primarily produced by cells of the immune system and binds to the heterodimeric receptor complex, IFNGR1/IFNGR2, on tumor cells, activating the JAK1/2-STAT1 signaling cascade." (PMID 33276788, 2020). "NK cells at the tumor site expressed low levels of granzyme B and CD57, as well as low levels of IFNγ." (PMID 33276569, 2020). "Up-regulated exosomal miR-let-7i in tumor-derived exosomes (TEX) can be taken up by mDCs, resulting in changes in intracellular levels of IL-6, IL-17, IL-1b, TGFbeta, SOCS1, KLRK1, IFNγ, and TLR4, thereby suppressing the immune response." (PMID 32299469, 2020). "Inhibition of MMP2/9 significantly increased the CD8+ T cell cytotoxicity and ability to eliminate tumor cells, and the CD8+ T cell cytotoxicity and killing ability was significantly stronger with IFNγ induction, which induced PD-L1 surface expression." (PMID 32988398, 2020). "In vivo studies, passive immunization against IFNγ and TNF-α of tumor-bearing rats allowed the intake of food, weight preservation, longer life, and better tolerance of larger tumors than in rats receiving a control antibody." (PMID 33158194, 2020).
tumor (continued). "The repression of CAR T‐cell infiltration was also evident in resected tumours at day 16 with Lck‐Cre;Ptpn2fl/fl;Stat5fl/+ CAR T‐cell cytotoxicity markers (TNF, IFNγ; induced by PMA/ionomycin ex vivo) being reduced to those in Ptpn2fl/fl control CAR T cells." (PMID 31803974, 2020). "Patient #1 and #4 showed CD8 reactivity against TD and TC, patient #3 only against TC treated with interferon-gamma (IFN), while patient #7 showed extensive reactivity against TC and TC-IFN with respectively 23.7% and 47.6% anti-tumor reactive CD8 cells." (PMID 32547707, 2020). "Given that IFNγ signaling is an important pathway used by T‐cells to kill tumor cells, the RAS‐mediated reduction of IFNγ signaling likely promotes immune escape." (PMID 33073260, 2020). "DFMO treatment led to the recruitment of activated (IFNγ+) CD4+ T cells, CD8+ T cells and NK cells and an increase in tumour‐killing M1 macrophages in the tumour microenvironment of an ovarian cancer mouse model." (PMID 33030764, 2020). "Purified astrocytes from tumor specimens revealed a reactive state marked by IL10 and IFNγ response resulting in a JAK/STAT pathway activation." (PMID 31186414, 2019). "The increased tumor protection correlated with higher tumor infiltration of antigen-specific CD8+ T cells, increased IFNγ production and degranulation potential." (PMID 30863405, 2019). "In the presence of IFNγ, MET-amplified tumour cells were more than 85% PD-L1 positive, with an increment in mean of fluorescence intensity (MFI) between 2 and 6 folds, depending on the cell line analysed." (PMID 30723303, 2019). "CXCR3 is essential for T cell recruitment into tumors and through the thymus and Th1 cells also produce IFNγ that induces additional production of CXCL9 and 10 to enhance the recruitment of cytotoxic CD8+ T cells into the tumor." (PMID 30873179, 2019). "In accordance with IFNγ release, EC17 also triggered CAR-T cell expansion identified as human CD3ε+ EGFRt+ events in mouse blood, and cells persisted up to 54 days in tumor-bearing animals (last measurement)." (PMID 30941303, 2019). "As a result, an increased IFNg production, a higher Th and CTL response, and a general decrease in the tumor growth rate and metastasis formation were observed in different types of cancer models." (PMID 30953535, 2019). "Another study performed on colon cancer has demonstrated that GPR109A, the receptor for short-chain fatty acids, functions as a tumor inhibitor in CRC, and the IFNγ can be used to activate GPR109A transcription silenced by DNA methylation." (PMID 31121824, 2019). "Tumor apoptosis, CD8+ cell infiltration and increased interferon-gamma (IFNγ) and interleukin-2 (IL-2) levels were only seen in PSMA-positive PC3 tumors." (PMID 31619289, 2019). "Glucose deprivation can prevent tumor infiltrating CD8+ T cells function by altering interferon gamma (IFN-γ) production, a key effector molecule having pro-inflammatory and enhanced anti-tumor properties." (PMID 31881671, 2019). "To further confirm that the effect of treatment was due to increased tumor recognition by CD8+ T-cells, we demonstrated activation of CD8+ T-cells by quantifying the secretion of IFNγ and CD107a, a degranulation marker, after treatments." (PMID 31196138, 2019). "IFNγ released by these cells activates JAK-STAT signaling in tumor and other cells of the tumor microenvironment which leads to increased PD-L1 surface display." (PMID 30873179, 2019). "Higher IL-12 expression was achieved through both an improved plasmid design, as well as reduced voltage and increased pulse length, which led to increased IFNγ and a higher CD8+/ CD4+ T-cell ratio with the tumor." (PMID 30323352, 2019). "A chronic PD-1 blockade progressively induced IFNγ and IFNβ transcription in the TME, with both IFNs in turn triggering PD-L1 and NOS2 expression on both tumor cells and leukocytes." (PMID 31481761, 2019).
tumor (continued). "In DFTD, it has been shown that tumour cells lack expression of MHC class I; however, this is reversible upon treatment with the inflammatory cytokine IFNγ." (PMID 31548856, 2019). "We have demonstrated that ablation of Treg cells in advanced primary tumors induces a strong anti-tumor response, which is dependent on CD4+ T cells and IFNγ." (PMID 31555258, 2019). "Second, Tα1 fused with the Fc domain of human IgG4 plays anti-tumor effects in the 4T1 and B16.F10 tumor xenograft models by upregulating CD86 expression, secreting IFNγ and IL-2, and increasing the number of tumor-infiltrating CD4+ and CD8+ T cells." (PMID 31555601, 2019). "Tumor vaccines stimulate the patients’ immune system, especially the response of specific CD8+ T cells; however, interferon gamma (IFNγ) produced by CD8+ and Th1 CD4+ cells regulate the expression of PD-L1." (PMID 31443694, 2019). "IFNγ also induces synthesis of PD-L1 transcription factor IRF1 and expression of checkpoint inhibitors including PD-L1 and PD-L2 on the surface of tumor, macrophages and dendritic cells." (PMID 31533832, 2019). "In both murine tumor models used in our studies, the levels of tumor MHC Class I (~ 90%) and PD-L1 in vivo are very similar within each treatment cohort, as is their capacity to mount an IFNγ response." (PMID 30898149, 2019). "In both OSCC animal models, SCNE significantly depressed circulating pro-cancer inflammatory cytokines (host and tumor-secreted) including NFkB, COX2, IL-1, IL-6, TNFα, and IFNγ." (PMID 31572681, 2019). "PD-L2 expression is induced by interferon gamma (IFN-γ) at the protein and mRNA levels in the T cell-inflammatory tumor microenvironment in cancer and can appear independently of PD-L1." (PMID 31464648, 2019). "This treatment promoted tumor growth, and resulted in lower percentages of tumoral CD8+ cells and granzyme B+ and IFNγ+CD8+ T cells." (PMID 31780645, 2019). "Further, it increased the production of interferon gamma (IFN-γ) and tumor necrosis factor alpha (TNF-α) by CD8+ T and NK cells in spleens as well as tumor microenvironment and increased the cytotoxic effects of CD8+ T and NK cells." (PMID 31817720, 2019). "OVA‐specific IFNγ‐producing CD8 T cells in spleen and tumor, as well as OVA‐tetramer positive CD8 T cells in the blood, were clearly detectable in the VSV‐GP group but only in about 30% of the mice." (PMID 30972741, 2019). "In particular, vaccine-induced CD4 T cells promote an inflammatory tumor microenvironment, by producing IFNg, which improves CTL killing activity and sensitizes tumor cells for recognition and direct killing by cytotoxic Th1 effectors." (PMID 31291991, 2019). "Tumor growth ([18F] FDG PET/CT imaging) and immune responses were monitored (flow cytometry, IFNγ ELISpot)." (PMID 30630527, 2019). "Meanwhile, conventional CD4 T cells and tumor-specific CD8 T cells displayed an activated profile as did recruited NK cells, with all these effector cells exhibiting an enhanced NF-κB and IFNγ-driven gene signatures." (PMID 31766350, 2019). "In the same co-culture experiments, the IFNγ secretion assay for CD4+ and CD8+ T cells showed some relationships among peripheral blood, normal lung tissues, and tumor tissues." (PMID 30796310, 2019). "Investigation of biomarkers of responsiveness to this combination therapy is of interest, including the role of tumor MHC Class I and PD-L1 level, capacity to mount a systemic IFNγ response, expansion of neoantigen-reactive T cells, and TCR clonality." (PMID 30898149, 2019). "The immunoconjugate 10_12-CL4 induced the death of tumor cells more efficiently than both the parental moieties, significantly increasing the secretion of IL-2 and IFNγ cytokines by lymphocytes, as well as LDH release by tumor cells." (PMID 31470510, 2019). "Specifically, IFNγ can induce the expression of PD-L1 through the JAK/STAT and PI3K-AKT signaling pathways to promote tumor immune escape." (PMID 30646912, 2019).
tumor (continued). "Further work from the same group indicates that a CD40 agonist triggers the release of IFNγ and CCL2 responsible for both the recruitment of monocytes/macrophages into the tumor and their polarization toward ECM-degrading cells." (PMID 31354719, 2019). "Compared to tumor-bearing mice that received CAR-T cells only, all EC17 treated tumor cohorts had ~30x (day 11) and ~10x (day 12) higher IFNγ production in mouse plasma, and the levels of this cytokine decreased naturally from 20 to 42 h later." (PMID 30941303, 2019). "NK cells potently secreted IFNγ, perforin and granzyme A in vitro after contact with GBM cells and abridged tumour mitochondrial function by diminishing both ATP production and maximal respiration." (PMID 31319548, 2019). "Mechanistically, these dual therapies are more effective than corresponding monotherapies at increasing the intra-tumoral presence of tumor-specific CD8+ T cells, CD4+FoxP3neg T cells as well as the levels of IFNγ and of mRNA coding for IFNγ and T-bet." (PMID 31244820, 2019). "Tumor HLA-1 expression can be regulated by various internal or external mechanisms specific to tumor cells within TME, especially interferon-gamma." (PMID 31166985, 2019). "Using either T cell-deficient nude mice, mice depleted of CD8 T cells as well as mice receiving IFNγ neutralizing antibodies, we identified IFNγ-secreting CD8 T cells as a major driver of PD-L1 tumor expression in vivo following Folfox treatment." (PMID 31191545, 2019). "The marginal IDO effect was proposed to be indicative of an effective IFNγ antitumor T cell response inducing, among others, immunomodulatory factors like PD-L1 and IDO expression in tumor cells." (PMID 30050535, 2018). "Lifileucel-induced in vitro IFNγ response to antibody coated beads (anti-CD3, anti-CD28, anti-CD137) and serum IP-10 levels post-treatment, correlates with reduction in tumor (Sum of Diameter of target lesions) and/or overall response." (PMID 30400822, 2018). "PD-L1 expression in tumour margins (i.e. at the tumour/stroma interphase) in SCC was related to favourable survival and most likely induced by IFNγ released by adjacent activated T cells." (PMID 30208866, 2018). "It represses CTL-mediated tumor cytotoxicity by altering the expression of perforin, granzyme A, granzyme B, Fas ligand (FASL), and IFNγ." (PMID 29486723, 2018). "We and other groups have previously investigated the methylation status of the IFNG locus in CD4+ T cells from LNs and tumours." (PMID 30075815, 2018). "IFNγ, which is produced by CD8+ T cells, can increase the expression of MHC class I antigens by tumor cells, thereby rendering them better targets for CD8+ T cells." (PMID 29441071, 2018). "Expression of IFNγ results in the upregulation of MHC expression, which increases the likelihood of neoantigen presentation in tumor cells and further boosts anti-tumor immune response." (PMID 30497521, 2018). "This treatment not only enhance the tumor cell killing, but also the activation of γδ T cells as seen by augmented CD69, CD25, IFNγ, and TNFα expression." (PMID 30038626, 2018). "In accordance with IFNγ induction, lung‐CM‐primed B220+CD11c+NK1.1+ cells clearly attacked co‐existing tumour cells." (PMID 29930175, 2018). "Cancer-associated fibroblasts, macrophages, T cells, and other accessory cells present in the tumor microenvironment are also known to modulate expression of the NKG2D receptor and production of interferon gamma (IFNγ) in NK cells." (PMID 29670543, 2018). "The tripartite peptide when combined with CpG induced T cell responses as measured by IFNγ and IL4 ELISpot analysis, in vivo CTL and protected mice from a tumour challenge." (PMID 30200528, 2018). "The ratio between effector CD8+IFNγ+ and CD4+IL-4+ T cells, the latter commonly endowed with a pro-tumor ability, was tipped in favour of effector cells in the SULT2B1b-4T1 TME." (PMID 30333826, 2018).
tumor (continued). "IFNγ produced within the TME induces CXCL9, CXCL10, and CXCL11 expression, which correlates with tumor infiltrating CTL and Th1-effector cells and with a positive survival rate in colorectal cancer." (PMID 30319638, 2018). "We used multiplex ELISA to demonstrate the presence of IL1B, IL6, IL8, IL10, IL18, TNF and IFNG in the cystic fluid and whole ACP tumour protein lysates." (PMID 29541918, 2018). "IFNγ is a major effector cytokine produced by CD4+ T cells, which can induce tumor-killing macrophages." (PMID 30190583, 2018). "Meanwhile, the baicalein therapy induced expansion of an IFNG and GZB-producing activated CD8+ T cell population in the tumor of mice." (PMID 30618763, 2018). "Adjuvant administration of oncolytic viruses upregulate the expression of pro-inflammatory cytokines such as IFNγ which would in turn increase JAK 1/2 signaling and antigen expression to augment tumor response to checkpoint blockade." (PMID 30514385, 2018). "IFNγ ELISPOT assays detected strong reactivity of Ted10 to mel-2400 and mel-2661 as well as another CCNI-editing positive tumour line, mel-2391, whereas Ted10 cells displayed only a background level response to the CCNI-editing negative mel-2559." (PMID 30254248, 2018). "CD8+ T cells in the tumor-dLN and tumor of both WT and PLT2 mice were also increased after Poly I:C immunotherapy, and were able to secrete increased IFNγ upon in vitro restimulation." (PMID 30383838, 2018). "Combination of M7824 and Ox/5-FU significantly decreased tumor volume and weight in the MC38 model and increased the frequency of p15E-reactive, IFNγ-producing CD8+ T cells." (PMID 30400835, 2018). "In this context, IFNγ is an inflammatory cytokine, which is able to enhance the expression of PDL-1 on CRC cells and immune-cells in the tumor sites." (PMID 29755670, 2018). "The presence of cytokines in the ACP tumours was also assessed by multiplex ELISA against IL1B, IL6, IL8 (CXCL8), IL10, IL18, TNF (TNFα) and IFNG (IFNγ), which revealed the expression of all of these but IFNG in protein lysates from eight human ACPs." (PMID 29541918, 2018). "Since IFNγ is often secreted by immune cell populations upon stimulation, we next analyzed the effects of LNT treatments on tumor-infiltrating immune cells." (PMID 30373628, 2018). "IFNγ induces the expression of some tolerant molecules, such as CTLA‐4, PD‐L1 and indolamine‐2,3‐ dioxygenase‐1 (IDO1) on/in tumor cells." (PMID 30039553, 2018). "Activated CD4 T-cells release pro-inflammatory cytokines, such as IFNγ, which in turn, upregulate MHC-II expression on tumours to allow for direct recognition by CD4 T-cells." (PMID 29570634, 2018). "γδ T cells can have a wide range of effects ranging from reshaping the tumor microenvironment, being integral in promoting a diverse cancer protective IgE repertoire through NKG2D stress surveillance, or IFNγ production." (PMID 30538697, 2018). "Percentages of tumor infiltrating CD4+ T and CD8+ T cells and the production of interferon gamma (IFN-gamma) were analyzed by flow cytometer." (PMID 30400822, 2018). "On the other hand, MSCs promoted cancer in progressive stages due to the elevation of proinflammatory cytokines (IFNγ, TNFα, IL6 and IL1β) expression in the tumor microenvironment." (PMID 30346985, 2018). "Blocking adenosine production with CPI-006 enhanced immune-cell mediated tumor killing (220pM) and reversed suppression of T cell proliferation (EC50, 70nM) and IFNγ secretion (EC50, 66nM)." (PMID 30400835, 2018). "miR-155 expression in T cells is required for maintaining the number of IFNγ-expressing CD4+ and CD8+ T cells and suppressing tumor growth." (PMID 30046565, 2018). "When used in combination, however, pP1A and ICBs significantly increased IFNg and IL12 production but also CD4 and CD8 T cell infiltration 10 days after tumor implantation." (PMID 30356111, 2018).